NKD2 (NKD inhibitor of Wnt signaling pathway 2)
Diseases named in the same sentence as NKD2 in open-access papers (continued):
Sharing a sentence is not in itself a finding about the gene and the disease.
renal fibrosis (4 papers, 2017 to 2025). A final common manifestation of a wide variety of chronic kidney diseases characterized by glomerulosclerosis and tubulointerstitial fibrosis. "The levels of the fibrotic biomarkers PAI-1 and naked cuticle homolog 2 (NKD2) were concomitantly decreased in the kidneys, with recent reports identifying NKD2 as a specific marker for myofibroblasts in human renal fibrosis." (PMID 38174337, 2023). "In mouse models where renal fibrosis was induced, finerenone attenuated pathological myofibroblast activation, collagen deposition, and expression of kidney plasminogen activator inhibitor-1 (PAI-1) and naked cuticle 2 (NKD2), key mediators of tissue fibrosis." (PMID 40149601, 2025).
acute myeloid leukemia (3 papers, 2022 to 2025). Acute myeloid leukemia (AML) is a group of neoplasms arising from precursor cells committed to the myeloid cell-line differentiation. "Decreased NKD2 expression has been reported to be associated with the poor outcome in cytogenetically normal acute myeloid leukemia patients." (PMID 36348408, 2022). "In acute myeloid leukemia, the epigenetic dysregulation of NKD2 is correlated with the dismal clinical outcome with patients." (PMID 36820951, 2023). "The prognostic value of NKD2 has been demonstrated in some other tumors, for example, hepatocellular carcinoma, ovarian cancer, acute myeloid leukemia." (PMID 36348408, 2022).
colon cancer (3 papers, 2011 to 2019). "Instead, a study in SW480 colon cancer mouse xenografts showed that treatment with JQ1 significantly downregulated miR-21 and reduced tumor growth and naked cuticle homolog 2 (Nkd2) expression and increased the apoptosis and β-catenin levels." (PMID 31780938, 2019). "Therefore we tested Wnt signaling in the colon cancer cells treated with curcumin, and our results showed that curcumin could inhibit the Wnt signaling by down-regulating β-catenin, which was mediated by up-regulating the Wnt signaling negative regulator Nkd2." (PMID 29225578, 2017).
glioblastoma (2 papers, 2012 to 2023). The most malignant astrocytic tumor (WHO grade IV). "In contrast, NKD2-hypermethylation occurred in 43% (13/30) of the primary glioblastoma tissues, while a super low rate was observed in astrocytoma (1/30)." (PMID 36969985, 2023).
glioma (2 papers, 2015 to 2022). A benign or malignant brain and spinal cord tumor that arises from glial cells (astrocytes, oligodendrocytes, ependymal cells). "NKD2 has been reported to be frequently methylated in human gliomas." (PMID 26124080, 2015).
thyroid cancer (2 papers, 2022 to 2023). "The results suggested that thyroid cancer pathway and several other cancer-related pathways were significantly activated in NKD2 highly expressed THCA patients." (PMID 36348408, 2022). "Notably, 9 various cancer-related pathways, including Thyroid cancer pathway, were significantly enriched, which implied that NKD2 was actually involved in cancer." (PMID 36348408, 2022).
bladder cancer (1 paper, 2018). "In order to explore the molecular mechanism of ZFAS1 in bladder cancer, we detected the effect of ZFAS1 on the expression of KLF2, NKD2, and EMT-associated genes (ZEB1, E-Cadherin, and Vimentin) by Western blot." (PMID 29678899, 2018). "The experiments in vitro suggested that knockdown of ZFAS1 repressed bladder cancer cell proliferation via up-regulating KLF2 and NKD2 expression, and inhibited cell migration and invasion via down-regulating ZEB1 and ZEB2 expression." (PMID 29678899, 2018). "Thus, knockdown of ZFAS1 repressed bladder cancer cell proliferation via up-regulating KLF2 and NKD2 expression, and inhibited cell migration and invasion via down-regulating ZEB1 and ZEB2 expression." (PMID 29678899, 2018).
Cerebral ischemia (1 paper, 2025). Restriction of arterial blood supply to the brain associated with insufficient oxygenation to support the metabolic requirements of the tissue. "NAP-induced down-regulation of various ER stress genes in males, including those encoding the pro-neuroinflammatory Nkd2, Hsph1 (Hsp110/105) and Fam107a (DRR1), which were shown to exacerbate cerebral ischemia, and Mertk, the mediator of alpha-synuclein fibril uptake." (PMID 39715923, 2025).
hepatocellular carcinoma (1 paper, 2022). A malignant tumor that arises from hepatocytes. "NKD2 has been indicated to be a potential prognostic biomarker and therapeutic target in hepatocellular carcinoma." (PMID 36348408, 2022).
melanoma (1 paper, 2017). A malignant, usually aggressive tumor composed of atypical, neoplastic melanocytes. "Moreover, the use of an anti-NKG2D blocking mAb strongly decreased NK92-, NKd1- and NKd2-mediated killing of T1 melanoma cells, demonstrating that NKG2D is an important determinant for the lysis of T1 cells by NK cells." (PMID 28423623, 2017).
metabolic bone disorder (1 paper, 2025). A group of disorders that affect the bones secondary to increased levels of minerals or deficient levels of minerals such as calcium, magnesium, phosphorus, and vitamin D. Representative examples are osteomalacia, osteoporosis, and Paget disease. "Taken together, the current research suggests that NKD2 may serve as a novel therapeutic target for metabolic bone disorders such as osteoporosis." (PMID 39552785, 2025).
sarcoma (1 paper, 2017). A usually aggressive malignant neoplasm of the soft tissue or bone. "Genes located in 5p that have been suggested as possible amplicon targets in sarcomas include NKD2, TERT, IRX2, TRIO, AMACR, SKP2 and RICTOR." (PMID 28652867, 2017).
tumor (30 papers, 2007 to 2025). "NKD2 methylation was significantly associated with reduction of NKD2 expression, and tumor stage (p < 0.05)." (PMID 26124080, 2015). "Further, it was also reported that curcumin strongly hindered tumor EMT through downregulating Nkd2-Wnt-CXCR4 signaling, then mediation of EMT-associated markers E-cadherin and vimentin expressions, resulting in a reduction of invasive and metastatic abilities in SW620 CRC cells." (PMID 35308223, 2022). "Naked cuticle homolog 2 (NKD2) has been recognized as an antagonist of Wnt/β-catenin signaling and a tumor suppressor." (PMID 39552785, 2025). "Western blot analysis demonstrated upregulation of NKD2 and IFIX in the OE‐IFIX and OE‐IFIX+Sh‐NKD2 groups, consistent with their tumour‐suppressive effects." (PMID 39833105, 2025). "NKD2 can suppress tumor growth and/or metastasis in osteosarcoma, esophageal cancer, and hepatocellular carcinoma, at least partly attributed to its inhibitory impact on Wnt/β-catenin signaling." (PMID 39552785, 2025). "Undoubtedly, we also found that NKD2 was expressed at higher levels in THCA tissues relative to that in tumor-free tissues." (PMID 36820951, 2023). "The tumor-suppressive function of NKD2 is reported in different cancers, due to its inhibition of the WNT signaling pathway." (PMID 36820951, 2023). "In the TCGA-THCA cohort, NKD2 expression was amplified in patients with advanced T(tumor) (T3/T4) and N(Node) (N1) stages." (PMID 36820951, 2023). "In THCA, there was an overwhelming enhancement of the NKD2 expression in tumor tissues compared with the tumor-free tissues." (PMID 36820951, 2023). "Curcumin inhibits tumor epithelial–mesenchymal transition by downregulating the Wnt signaling pathway and upregulating NKD2 expression in cancer cells." (PMID 34456716, 2021). "Published studies indicated that ZFAS1 directly repressed KLF2 and NKD2 expression to promote tumor cell proliferation, and induced ZEB1 to enhance the epithelial–mesenchymal transition (EMT) and metastatic ability." (PMID 29678899, 2018). "The tumor weight was less in the NKD2 expressed group compared to the unexpressed group (101.75 ± 34.20 mg vs. 213.13 ± 51.15 mg, p < 0.01)." (PMID 26124080, 2015). "However, the OE‐IFIX+Sh‐NKD2 group exhibited the smallest tumour volume, suggesting that IFIX retains its antitumour effects even in the absence of NKD2." (PMID 39833105, 2025). "Importantly, the OE‐IFIX+Sh‐NKD2 group exhibited the smallest tumour volume, with significant differences compared to all other groups, including OE‐IFIX and Sh‐NKD2 (p < 0.0001)." (PMID 39833105, 2025). "Here, we hypothesise that IFIX exerts its tumour‐suppressive effects in OSCC by regulating NKD2 and the Wnt signalling pathway, which in turn affects EMT and cell adhesion." (PMID 39833105, 2025). "Next, we selected several EZH2 or LSD1 potential targets (P15, P21, KLF2, PTEN, KLF2, LATS2, RND3, and NKD2) with tumor-suppressive role, and hypothesized that some of which might be associated with LINC00665-mediated carcinogenicity." (PMID 34094920, 2021). "KEGG pathway enrichment analysis showed that CCNE2, MYC, CREB3L4, and NKD2 are involved in many tumor-related pathways, suggesting that these genes may play an essential role in cancer development." (PMID 28056099, 2017). "NKD2 has been reported to suppress tumor growth and metastasis in osteosarcoma." (PMID 26396173, 2015). "By modulating NKD2, IFIX exerts significant control over cell proliferation, migration, invasion and EMT, underscoring its potential role in tumour suppression." (PMID 39833105, 2025). "Thus, the tumor promotion imposed by NKD2 might be through TNF-α/NF-κB signaling pathway." (PMID 36820951, 2023).
tumor (continued). "We evaluated the methylation status of 12 putative tumor-suppressor genes (ARHI, RASSF1A, HIN-1, RARβ2, hMLH1, the 14-3-3 σ gene, RIZ1, p16, the E-cadherin gene, RIL, CDH13, and NKD2), LINE1, ER, and PGRB in both culture cell lines and primary cancer tissues." (PMID 17764565, 2007). "Twelve tumor-suppressor genes: ARHI, RASSF1A, HIN-1, RARβ2, hMLH1, 14-3-3 σ, RIZ1, p16, E-cadherin, RIL, CDH13, and NKD2 were selected for this methylation study." (PMID 17764565, 2007). "Microarray analysis of both localized and metastatic tumors developed from these models revealed downregulation of the naked cuticle homolog 2 (NKD2) gene, a negative regulator of Wnt signaling, that was found to be important for the suppression of OS tumor growth and metastasis." (PMID 39091911, 2024). "In contrast, DKK3 was more highly expressed in human OSA cells overexpressing NKD2 and in tumor tissue, and also in tumor tissue compared to non-affected bone in naturally occurring canine OSA." (PMID 36570509, 2022). "Moreover, curcumin attenuated tumor EMT by blocking the Wnt signaling pathway and elevating the expression level of naked cuticle homolog 2 (NKD2) in SW620 cells." (PMID 34276374, 2021). "Next, we selected several EZH2, LSD1 or DNMT1 potential targets (P15, P21, LATS2, RND1, KLF2, NKD2, PTEN) with tumor-suppressor function and SPRY4, and hypothesized that they may involve in the contributions of SPRY4-IT1 to CCA progression." (PMID 29642935, 2018). "Additionally, in tumor tissues collected from A549 xenograft model, ART and its derivatives effectively reduced Wnt5-a/b, LRP6, and Dvl2 but significantly increased both NKD2 and Axin2 (p < 0.001)." (PMID 27119499, 2016). "However, the tumor/normal log2 ratios of AXIN1, CREBBP, GSK3A, and NKD2 in the BRAF wildtype samples were low (−0.26 median, 0.12 standard deviation) compared with those in the BRAF mutated samples (−0.02 median, 0.12 standard deviation)." (PMID 23324568, 2013). "The heatmap showed that 12 tumor suppressors formed into two clusters: cluster 1 contains seven downregulated tumor suppressors including PTEN, PSME1, DNAJB1, HSPH1, DEDD2, PAK1IP1, and MIR1244-3; and cluster 2 contains five upregulated tumor suppressors (OSGIN1, IFI27L1, MTCH2, NKD2, and IBTK)." (PMID 34571936, 2021).
cancer (19 papers, 2007 to 2025). A tumor composed of atypical neoplastic, often pleomorphic cells that invade other tissues. "In 20 cases of loss/reduced expression of NKD2 cancer samples, 17 cases were methylated." (PMID 26396173, 2015). "NKD2 plays key role in the development of many cancer types, such as breast cancer, hepatocellular carcinoma, oesophageal cancer and osteosarcoma." (PMID 39833105, 2025). "LINC00922 enhances cell viability and promotes the invasion and metastasis of cancer cells by inhibiting the downstream target NKD2, and also promotes EMT by activating the Wnt signaling pathway." (PMID 37901333, 2023). "Our findings for the first time suggested the promoting role of NKD2 in cancer by the TNFA/NF-κB signaling pathway." (PMID 36820951, 2023). "Given the involvement of NKD2 in carcinogenesis and progression, we queried its expression in pan-cancer based using the clinical database from the Cancer Genome Atlas (TCGA) and GETx." (PMID 36820951, 2023). "NKD inhibitor of WNT signaling pathway 2 (NKD2) is an emerging player in cancer onset and progression." (PMID 36820951, 2023). "As an inhibitor of the Wnt signaling pathway, NKD2 is suggested to regulate the wnt signaling pathway in cancers." (PMID 36820951, 2023). "Aberrant expression and epigenetic alterations of NKD2 have been increasingly evidenced to play crucial roles in many cancers." (PMID 36348408, 2022). "TET-1 was deemed as a novel cancer suppressor gene: the increased levels in this study showed that it upregulated NKD2, which ultimately inhibited the WNT pathway." (PMID 36015440, 2022). "At the same time, we found DAAM1 and NKD2 gene, two of our hub genes involved in Wnt pathway, worked as intermediate elements in signal regulation across different cancer." (PMID 32766227, 2020). "Tankyrase-mediated degradation of HectD1 or NKD2 would have a similar impact on cancer cell growth as degradation of Axin, to stabilize β-catenin and promote growth." (PMID 29263426, 2017). "Restoration of NKD2 expression suppressed cell proliferation, colony formation, cell invasion and migration, induced G2/M phase arrest, and sensitized cancer cells to docetaxel." (PMID 26396173, 2015). "Notably, several cancer-associated genes are located within a 1 Mb proximity including CLPTM1L, TERT, BRD9, TRIP13, NKD2, LPCAT1, and IRX4." (PMID 40278994, 2025). "Based on the TCGA database, we found the amplification of NKD2 in pan-cancer including THCA." (PMID 36820951, 2023). "Therefore, we first assessed the NKD2 expression in pan-cancers and THCA and delineated the clinical significance in THCA, and analyzed the function of NKD2 during THCA malignancy by both gain and loss of functional assays." (PMID 36820951, 2023). "For instance, highly expressed NKD2 in ovarian cancer constrain cancer cell growth and survival." (PMID 36820951, 2023). "LINC00922 binds to DNMT1, DNMT3A, and DNMT3B and is enriched in the promoter region of the downstream tumor suppressor NKD2, thereby inhibiting its expression through methylation, which ultimately activates the Wnt signaling pathway and promotes cancer progression." (PMID 37901333, 2023). "NKD2 was previously reported to be regulated by promoter region methylation and it was the target of some lncRNAs or miRNAs in the regulation of several cancers, which should be further studied in our future research." (PMID 36348408, 2022). "NKD2 has been increasingly evidenced to play crucial roles in many cancers, except for THCA." (PMID 36348408, 2022). "In 27 cases of NKD2 expressed cancer samples, 4 cases were methylated." (PMID 26396173, 2015). "Consequently, we inferred that subjects with FCH carrying SMYD3 or NKD2 gene deletions may have a higher cancer incidence." (PMID 33431054, 2021). "Finally, CDK2, LST1, NKD2 and RASL11B have also been implicated in a variety of cancer types." (PMID 22087225, 2011).
cancer (continued). "To understand the interplay between NKD2 and EMT in CAL‐27 cancer cells regulated by IFIX, we silenced NKD2 and then rescued it by transfection with a plasmid‐overexpressing IFIX." (PMID 39833105, 2025). "Therefore, NKD2 might have dual functions in different cancers." (PMID 36820951, 2023). "NKD2 is a negative regulator of the WNT signaling pathway, and its overexpression inhibited cancer cell proliferation, migration, and invasion." (PMID 34571936, 2021). "Despite differences compared to some cancers, this outcome agreed with DKK3 knockdown in cells overexpressing NKD2 which exhibited increased proliferation, indicating a possible mechanism of NKD2 induced metastasis, although the authors noted more work into the mechanisms was required." (PMID 36570509, 2022). "Besides, compared with the results of the differential analysis, our results showed that most of dynamic network biomarkers identified by node entropy, such as NKD2 or DAAM1, located in upstream in many important cancer-related signaling pathways regulated intergenic signaling within pathways." (PMID 32766227, 2020). "Here, we performed further analyses and characterization of HBV integrations identified by our recently reported VIcaller platform in recurrent or known HCC genes (such as TERT, MLL4, and CCNE1) as well as non-recurrent cancer-related genes (such as CSMD2, NKD2, and RHOU)." (PMID 33557409, 2021).
NKD2 also shares sentences with these, for which no sentence is quoted: lung carcinoma (3 papers); ovarian carcinoma (2); astrocytoma (1); brain cancer (1); metastatic tumors (1); osteoporosis (1); pancreatic cancer (1); viral myocarditis (1).